INSR (insulin receptor)
Diseases named in the same sentence as INSR in open-access papers (continued):
Sharing a sentence is not in itself a finding about the gene and the disease.
Insulin resistance (continued). "During diabetes, an increased level of TNF-α showed the effect on the insulin receptor and decreased the insulin sensitivity, while IL-6 shows the effect on the glucose via altering the insulin receptor, IRS, glut-4, which increase the incidence of insulin resistance." (PMID 35542112, 2018). "Previous studies have been conducted on many candidate genes for PCOS, principally related to reproductive hormones, insulin resistance, and chronic inflammation, including follicle-stimulating hormone receptor (FSHR), insulin receptor (INSR), and tumor necrosis factor (TNF)." (PMID 29232372, 2017). "PI3Ks modulate oxidative stress and insulin resistance via the DHA Signaling (network 1) and the Insulin Receptor Signaling (network 2) pathways and the Jnk domain (network 1) and is highlighted by significant scoring of the Type II Diabetes Mellitus Signaling pathway (network 5)." (PMID 29326659, 2017). "Along with the decrease in the phosphorylation of insulin receptor substrates (IRS-1 and IRS-2) and in PI3-K activity observed in insulin resistance, the translocation of glucose transporters and the activity of key enzymes implicated in glucose homeostasis are also reduced." (PMID 28259166, 2017). "Moreover, miRNAs of this family regulate glucose metabolism and peripheral insulin resistance by targeting IGF1R, insulin receptor (INSR), and insulin receptor substrate-2." (PMID 28974990, 2017). "All features of type 2 DM, such as obesity, insulin resistance, and hyperinsulinemia, have been shown to occur in mice with neuron-specific disruption of the insulin-receptor gene (NIRKO) without any disturbance in brain development." (PMID 28824543, 2017). "Insulin resistance due to insulin receptor (INSR) dysfunction is associated with none of these, but when due to dysfunction of the downstream kinase AKT2 phenocopies obesity-related insulin resistance." (PMID 27766312, 2016). "Recently, we reported the requirement of BBS proteins for insulin receptor trafficking to the cell membrane and demonstrated that disruption of BBS proteins interfere with insulin receptor surface expression leading to insulin resistance and dysregulated glucose metabolism." (PMID 26926121, 2016). "In humans mutations in the insulin receptor lead to a similar phenotype as the LIRKO mice, with severe insulin resistance, hyperinsulinaemia and hyperglycaemia, but not elevated levels of serum TGs." (PMID 25740151, 2016). "Female but not male mice with absence of the insulin receptor in the brain exhibit hyperinsulinemia and peripheral insulin resistance with lower LH levels and subfertility, indicating a neuronal action of insulin to regulate LH release in female rodents." (PMID 25780937, 2015). "Individuals with insulin resistance have either decreased levels or absence of insulin receptor expression (InsR) and subsequent hyperglycemia." (PMID 25785174, 2015). "As fat-specific insulin receptor deficient mice (FIRKO mice) failed to exhibit glucose intolerance, we examined the contribution of insulin resistance in liver." (PMID 26615883, 2015). "Evidences support the insulin resistance observed in STZ-diabetic animals, mainly characterized by a reduction in the tyrosine kinase activity of the insulin receptor (IR), despite the increased IR number and decrease in the AKT activation (phosphorylation in serine-473 residue)." (PMID 26064170, 2015). "Insulin resistance in diabetic patients may lead to cancer by directly affecting the cancer cells via overexpression of insulin-like growth factor 1(IGF1) and insulin receptor (IR) substrate proteins." (PMID 25652009, 2015). "To test our hypothesis, we treated wildtype mice or β2KO mice with etanercept for two months and measured proteins involved in insulin resistance and signaling, including TNFα, SOCS3, insulin receptor (IR), and apoptotic markers." (PMID 25138272, 2014).
Insulin resistance (continued). "In a mouse line with insulin receptor deletion specifically in the liver (LIRKO), pancreatic β-cell mass is dramatically increased, along with phenotypes including insulin resistance, severe glucose intolerance, and a failure of insulin to suppress hepatic glucose production." (PMID 25212743, 2014). "In cancer patients with insulin resistance, the consequent high levels of circulating insulin, together with overexpression of the insulin receptor by the tumour cells, stimulate significant nonmetabolic effects." (PMID 23983688, 2013). "Furthermore, the PNS of ob/ob mice has alterations in cellular mechanisms of insulin resistance, including decreased DRG insulin receptor expression and upregulation of JNK activity in the sciatic nerve." (PMID 24252636, 2013). "Activation of JNK has been established as a stress-mediated inducer of insulin resistance in diabetic animal models via phosphorylation of IRS-1 at Ser-307, leading to inactivation of IRS-1 by interfering with the interaction of the insulin receptor and IRS-1 and promoting IRS-1 degradation." (PMID 21119656, 2011). "Mice heterozygous for Tace are protected from diet-induced insulin resistance and diabetes, whereas pharmacologic TACE-inhibition reduced hyperglycemia and vascular inflammation in diabetic mice heterozygous for the insulin receptor, as well as in fructose-fed rats." (PMID 21980496, 2011). "Insulin resistance in Dahl S rats does not seem to develop as a result of an alteration in the insulin receptor number, affinity, binding parameters, mRNA levels or tissue distribution in liver, muscle and kidney tissues." (PMID 18570670, 2008). "Although both TAG and DAG accumulations in skeletal muscle were reported to be correlated with insulin resistance, DAG (a precursor of TAG synthesis) is proposed to directly impair insulin sensitivity by inactivating insulin receptor activity through activation of the protein kinase C." (PMID 15507149, 2004). "The transcription factor Forkhead Box 1 (FOXS1) is an emerging biomarker in liver fibrosis, and it could be that it is essential for insulin resistance to initiate fibrotic pathways, as CRISPR FOXS1 knockout in human LX2 HSCs increased the kinase activity of the insulin receptor." (PMID 40985048, 2025). "In terms of insulin resistance, IL-1β interferes with insulin signaling by activating stress kinases like JNK and inhibitor of nuclear factor kappa B kinase subunit beta (IKKβ), which phosphorylate insulin receptor substrate proteins and disrupt downstream insulin signaling cascades." (PMID 38044678, 2024). "Insulin resistance may be linked to systemic chronic inflammation related to obesity, where inflammatory factors can impede the phosphorylation of the insulin receptor substrate and PI3K in the insulin signaling pathway, resulting in obstructed signal transduction and insulin resistance." (PMID 38167106, 2024). "This condition could explain why mice with severe hepatic insulin resistance, due to the absence of hepatic insulin receptor substrates (IRSs) IRS1 and IRS2, exhibit reduced obesity and lower circulating levels of FGF21." (PMID 39409124, 2024). "Moreover, the HOMA-IR, an index of IR, and the protein expression of insulin receptor in the liver resulted significantly reduced in obese mice fed AFA, confirming that microalgae extracts can effectively prevent the insulin resistance due to excess fat consumption." (PMID 38067134, 2023). "We also investigated whether activation of brain insulin signaling or inhibition of insulin receptor signaling, as occurs in brain insulin resistance, could impact insulin BBB transport by delivering insulin or the selective insulin receptor antagonist S961, directly to the brain." (PMID 37076875, 2023).
Insulin resistance (continued). "Differential display experiments on mRNA extracted from the muscle of insulin receptor haplo-insufficient mice (Insr+/−) with or without insulin resistance mice identified a marked decrease in TIMP3 expression in Insr+/− mice with insulin resistance compared to insulin sensitive animals." (PMID 37445827, 2023). "Continuous exposure to increased insulin levels downregulates plasma membrane insulin receptor expression, which in turn augments insulin resistance; however, we did not obtain any evidence suggesting that prolonged exposure to elevated insulin levels downregulates insulin receptor expression." (PMID 37443824, 2023). "Altogether, these findings suggest that total and methanolic PSC-FEs could protect HepG2 cells from insulin resistance, as evidenced by enhancement of glucose uptake, enhancement of AMPK and AKT activation, and also an increase in expression of INSR, GLUT1, and GLUT4." (PMID 37158952, 2023). "One recent study with insulin receptor muscle over‐expression (IRMOE) demonstrated similarities with our in vitro model, such as increased basal AKT phosphorylation and impaired insulin‐stimulated AKT phosphorylation, indicative of a significant level of post‐receptor insulin resistance." (PMID 34921686, 2022). "In developing hypertension, insulin receptor (IR) or insulin receptor substrate (IRS) signaling has a mechanistic role independent of glucose homeostasis and plasma insulin levels, indicating that insulin resistance is involved in the pathogenesis of hypertension." (PMID 35455055, 2022). "However, PON1 counteracts insulin resistance, not using the insulin receptor, but acting through an enhanced expression of the PI3K/Akt signaling pathway." (PMID 36290747, 2022). "Interestingly, variations in the IGFBP7 isoform appeared to differentially bind the insulin receptor, possibly explaining why some obese patients develop insulin resistance whereas others do not." (PMID 34025667, 2021). "Although roles for JNK1 signalling in mediating insulin resistance through inhibition of insulin receptor signalling is well established in the periphery and CNS, as yet there is limited direct data available examining the role of JNK signalling in glia in the context of obesity insulin resistance." (PMID 31765625, 2020). "Insulin resistance is increasingly being shown to be important in PD as a potential therapeutic target and has a high prevalence in non-diabetic PD patients, additionally insulin receptor signaling pathways are disturbed in PD." (PMID 32205467, 2020). "Indeed, insulin resistance is related with changes in levels of two inositol stereoisomers, such as D-Chiro-inositol (DCI) and Myo-inositol (MI), that have been proposed to act as second messengers in insulin receptor cell signaling." (PMID 32650579, 2020). "Restoration of HMGA1 protein expression in these subjects' cells enhanced INSR gene transcription and restored cell-surface INSR protein expression, thus confirming that defects in HMGA1, by decreasing INSR protein production may indeed induce severe insulin resistance." (PMID 30034366, 2018). "Mice specifically lacking the insulin receptor in the liver exhibit severe insulin resistance and hyperglycemia after feeding, indicating that hepatic insulin receptor signaling plays an essential role in the regulation of hepatic and systemic glucose homeostasis." (PMID 29749571, 2018). "To investigate whether mitochondrial function is regulated by insulin signaling, we analyzed muscle and liver of insulin receptor (IR)+/−-insulin receptor substrate-1 (IRS-1)+/− double heterozygous (IR-IRS1dh) mice, a well described model for insulin resistance." (PMID 28556799, 2017). "In diabetes, which is characterised by an absence of insulin or increased peripheral insulin resistance (or both), a reduction in insulin receptor (IR) to IRS to PI3K to Akt signalling leads to acceleration of atherosclerosis because of the loss of anti-atherogenic insulin signalling." (PMID 27514532, 2016).
Insulin resistance (continued). "Indeed, in 2008, it was reported that ablation of the insulin receptor in mouse liver, although inducing severe systemic insulin resistance, did not increase liver triglyceride or liver weight." (PMID 27899914, 2016). "The primary role of the liver in the development of insulin resistance is demonstrated by the fact that insulin resistance occurs in liver‐specific insulin receptor‐knockout mice, but not in muscle‐ or fat‐specific insulin receptor‐knockout mice." (PMID 27095270, 2016). "This phenomenon may be attributed to the implication of “INSR,” which only represents the secretion function of β-cell regardless of the influence of insulin resistance." (PMID 25741510, 2015). "It has been reported that ER stress inhibits insulin receptor signaling via the promotion of the c-Jun N-terminal kinase (JNK)-dependent serine phosphorylation of insulin receptor substrate (IRS)-1, subsequently leading to insulin resistance in mouse models of obesity." (PMID 26174230, 2015). "Moreover, without affecting insulin receptor-mediated signal transduction, TNF-α can induce insulin resistance in adipocytes, characterized by loss of insulin receptor substrate-1 and GLUT4 expression." (PMID 24465695, 2014). "Moreover, more evidence has accumulated implicating that hyperinsulinema and insulin-resistance, both present in GHRLD mice, could lead to deregulation of insulin receptor (IR), especially its IR-A isoform, in malignant cells and promote tumor progression." (PMID 25566190, 2014). "Thus, the extreme hyperinsulinemia in the ob/ob mice may be promoting insulin receptor downregulation and contributing to PNS insulin resistance." (PMID 24252636, 2013). "In mice lacking the INSR in osteoblasts, a decrease in both total OC and ucOC was observed in serum, leading to decreased bone formation and development of peripheral adiposity and insulin resistance." (PMID 23691179, 2013). "Interestingly, the phenotype of transgenic mice lacking the INSR in osteoblasts, with decreased circulating OC, decreased bone formation and insulin resistance, are similar to the clinical features characterizing CS patients." (PMID 23691179, 2013). "However, insulin resistance specifically refers to the inability of insulin to promote cellular glucose uptake, which is mediated primarily via the phosphatidylinositol-3 kinase (PI3K) signalling pathway downstream of the insulin receptor." (PMID 21054880, 2010). "A recent report demonstrated that mice lacking insulin receptor expression in the myeloid lineage were protected from insulin resistance when fed a high-fat diet, possibly due to reduced systemic inflammation and decreased monocyte/macrophage infiltration of white adipose tissue." (PMID 21054880, 2010). "While hepatic PKCε activation was previously proposed to mediate hepatic insulin resistance via phosphorylation of the insulin receptor in hepatocytes, the lack of protection against diet-induced insulin resistance in hepatocyte-specific PKCε knockout mice brings this hypothesis into question." (PMID 40522859, 2025). "Skeletal muscle is the major site of insulin-mediated glucose uptake, and previous PCOS data have shown an intrinsic defect in insulin receptor signaling as a potential mechanism of insulin resistance, which may explain the negative impact on muscle mass reported in some studies." (PMID 37796920, 2023). "A systematic assessment of ovarian pathology in severe insulin resistance (SIR) has not been conducted, although scattered reports have described massive, bilateral ovarian enlargement and ovarian neoplasia associated with severe genetic insulin receptor dysfunction (Donohue syndrome)." (PMID 33901270, 2021). "A study including 183 individuals (127 individuals without insulin resistance and 56 with insulin resistance) indicated that trans fat intake impairs insulin sensitivity affecting insulin signaling via intracellular kinases, which alters insulin receptor substrates." (PMID 34681504, 2021).
Insulin resistance (continued). "The overexpression of p85α weakens signal transmission and causes insulin resistance by disrupting the activity of the p85α/p110 complex and the connection between PI3K and IRS, which indicates that p85α subunits play a negative role in PI3K signaling downstream of the insulin receptor." (PMID 33149760, 2020). "Thus, PIK3R1 C-terminal mutations impair insulin signaling only in some cellular contexts and produce a subphenotype of insulin resistance resembling INSR dysfunction but unlike AKT2 dysfunction, implicating PI3K in the pathogenesis of key components of the metabolic syndrome." (PMID 27766312, 2016). "In addition, the elevated expression of T-cad was suggested to be involved in the pathogenesis of insulin resistance in endothelial cells through the mechanism of chronic activation of the Akt/mTOR-dependent negative feedback loop and the increased degradation of insulin receptor substrate." (PMID 24136461, 2014). "The site of betaine’s action in normalizing insulin resistance appears to be at the level of tyrosine phosphorylation of IRS1, but not at the phosphorylation of insulin receptor nor at the amount of insulin receptor." (PMID 39119463, 2024). "The activation of JNK promotes the phosphorylation of insulin receptor substrate (IRS-1) at serine residues that leads to negative regulation of insulin signal transduction and induces insulin resistance." (PMID 35454131, 2022). "These events eventually stimulate the insulin signaling pathway by activating insulin receptor and GLUT-4 (data not shown) and thus reverse insulin resistance." (PMID 33917607, 2021). "As expected and consistent with the development of insulin resistance, HSu diet decreased insulin receptor expression and GLUT4 levels by 23.89 and by 27.00%, respectively, without any effect on insulin receptor and Akt phosphorylation." (PMID 32411098, 2020). "Thus, the aims of this study were to investigate in DM skeletal muscle biopsies if beyond INSR missplicing, altered IR protein expression could play a role in insulin resistance and to verify if the lack of insulin pathway activation could contribute to skeletal muscle wasting." (PMID 30901379, 2019). "Thus, the aims of this study were to further investigate in DM ex vivo muscle biopsies if beyond INSR missplicing, altered insulin receptor (IR) expression could play a role in insulin resistance and to verify if the lack of insulin pathway activation could contribute to skeletal muscle atrophy." (PMID 30901379, 2019). "Within SIR, there is a continuum of insulin resistance, ranging from Donohue syndrome (DS) with no remaining insulin receptor function to the milder phenotypes of Rabson–Mendenhall syndrome (RMS) and type A insulin resistance." (PMID 29695048, 2018). "In addition, as other studies have shown that insulin receptor expression and signaling is dependent on CAV1, increased expression of CAV1 in diabetic patients and mouse models may indicate an attempt to improve signaling under conditions of increased insulin resistance." (PMID 24608114, 2014). "In aged adiponectin knockout mice, the chronic absence of adiponectin leads to insulin resistance in the hippocampus, characterized by the decreased phosphorylation of AMPK, Akt, and PI3K, despite normal insulin plasma levels and insulin receptor expression in the hippocampus." (PMID 40717739, 2025). "Currently, it has been observed that ERS-induced insulin resistance may not depend on the JNK pathway, but on the downregulation of insulin receptor expression via autophagy pathway." (PMID 40302954, 2024). "Many reports have shown that AT2R activation reverses the negative action of AT1R on insulin receptor signaling (reviews:) and this is one of the mechanisms by which AT2R might exert its beneficial effects on insulin resistance." (PMID 29971102, 2018).